RCC1 (regulator of chromosome condensation 1)
Diseases named in the same sentence as RCC1 in open-access papers (continued):
Sharing a sentence is not in itself a finding about the gene and the disease.
lung carcinoma (5 papers, 2017 to 2025). "In Kaplan‐Meier plotter, Prognoscan and TISIDB databases, it was found that higher expression of RCC1 was associated with poor survival and prognosis in lung cancer." (PMID 33630417, 2021). "Studies in breast and lung cancer models have linked RCC1 overexpression to increased tumor invasiveness and resistance to apoptosis, indicating that RCC1 may be crucial for cancer cell survival under therapeutic stress." (PMID 40163507, 2025). "We found that lncRNA-MIR22HG and RCC1 were presented with some genes that known to cause tumorigenesis, cancer progression and resistance in other cancer systems, suggesting that these two lncRNAs interact with genes that necessary for drug resistance in lung cancer." (PMID 28968955, 2017). "Our findings also highlight the significant impact of RCC1 on metastatic behavior, as RCC1-silenced cells exhibited diminished migration and invasion capabilities in both breast and lung cancer models." (PMID 40163507, 2025). "By elucidating RCC1’s role in breast and lung cancer, this study aimed to identify potential therapeutic pathways to target its oncogenic functions." (PMID 40163507, 2025). "This opens the possibility of combining RCC1 inhibitors with immunotherapies, particularly in lung cancer, where immune checkpoint inhibitors have shown clinical success." (PMID 40163507, 2025). "Elevated RCC1 expression in breast and lung cancers is closely tied to enhanced tumor cell survival, proliferation, and metastasis, positioning it as a promising therapeutic target." (PMID 40163507, 2025). "Despite growing evidence of RCC1’s role in oncogenesis, its specific contributions to breast and lung cancer remain poorly understood." (PMID 40163507, 2025). "Our study demonstrates that RCC1 is a crucial regulator in breast and lung cancer progression, influencing key cellular processes such as survival, proliferation, and metastasis." (PMID 40163507, 2025). "Studies have shown that high RCC1 expression correlates with poor survival outcomes in cancers such as breast and lung cancer, likely due to its role in enhancing proliferation, invasion, and apoptosis resistance." (PMID 40163507, 2025). "In our study, RCC1 was found to play a multifaceted role in the development of breast and lung cancers by promoting cell viability, migration, and invasion while inhibiting apoptotic responses." (PMID 40163507, 2025). "This study aimed to clarify RCC1’s role in cancer progression through an in-depth analysis of its effects on cell survival, apoptosis, and metastasis in breast and lung cancer models." (PMID 40163507, 2025). "In conclusion, our study highlights the potential role of RCC1 in cancer biology, particularly in breast and lung cancer models." (PMID 40163507, 2025). "Based on the expression level of RCC1 in lung cancer and the survival analysis from the public database, we next performed experiments to verify the regulation of RCC1 in proliferation, apoptosis and cell cycle." (PMID 33630417, 2021). "On the other hand, in Oncomine database, we also proved that the expression of RCC1 in lung cancer was significantly higher than that in normal tissues of lung." (PMID 33630417, 2021). "In contrast, the high expression of RCC1 is associated with poor OS, FP and PPS for lung cancer (all p < 0.05)." (PMID 34298996, 2021). "This indicates that RCC1 may have different prognostic effects in variable lung cancer subtypes, but further research is needed to clarify its relevance." (PMID 34298996, 2021). "In lung cancer treatment, when the PI3K-Akt pathway is inactivated, curcumin (DMC) enhanced the sensitivity of drug-resistant lung cancer cells to cisplatin by downregulating the expression of thymidine phosphorylase and RCC1." (PMID 35684449, 2022).
colon carcinoma (4 papers, 2021 to 2025). "Furthermore, Kaplan–Meier analysis demonstrated that high RCC1 expression was associated with significantly worse overall survival in patients with colon cancer (P < 0.05)." (PMID 41281944, 2025). "Our results align with this, showing that high RCC1 protein expression is an independent unfavorable prognostic factor in colon cancer." (PMID 41281944, 2025).
prostate carcinoma (4 papers, 2020 to 2024). A carcinoma that arises from epithelial cells of the prostate gland. "In addition, although the knockdown of KPNB1 in advanced stage prostate cancer did not affect the expression of total RCC1, it did effectively reduce the expression of downstream cycle regulators and phosphorylation of RCC1, eventually leading to cycle arrest." (PMID 33102517, 2020).
glioma (3 papers, 2022 to 2025). A benign or malignant brain and spinal cord tumor that arises from glial cells (astrocytes, oligodendrocytes, ependymal cells). "Our study suggests that TRIM24, IDH1, LBR, HMG20B, USP49 and RCC1 were all highly expressed in glioma tissues and gliomar cell lines both at the mRNA and protein level." (PMID 36246611, 2022). "The RT-qPCR assay showed that the six signature genes (TRIM24, IDH1, LBR, HMG20B, USP49, and RCC1) were up-regulated in glioma cell lines in mRNA expression level." (PMID 36246611, 2022). "However, although many studies regard RCC1 as an onco-marker, differences in RCC1 expression in gliomas and control tissue samples remain inconsistent across various sources." (PMID 41373435, 2025). "To summarize, since RCC1 acts as one of the key cell cycle regulators and controls Ran activation, it is a promising target for studying its role in the development of various tumors, including gliomas." (PMID 41373435, 2025). "Combined with data on the increased expression of the RCC1 gene in gliomas, this suggests that a disruption of its normal localization and level of expression may be associated with mechanisms of oncogenesis." (PMID 41373435, 2025).
leukemia (3 papers, 2019 to 2023). A malignant (clonal) hematologic disorder, involving hematopoietic stem cells and characterized by the presence of primitive or atypical myeloid or lymphoid cells in the bone marrow and the blood. "Taken together, these data indicated that the combination of CHI with CLA exerts its anti-leukemia effect by targeting c-Myc/RCC1 signaling in AML cells." (PMID 36849955, 2023). "In the present study, we observed the synergistic anti-leukemia effect of CHI combined with CLA by inducing cell growth arrest, cell cycle arrest, and apoptosis in AML cells and identified the underlying mechanisms of the synergy through targeting HDAC2/c-Myc/RCC1 signaling in AML." (PMID 36849955, 2023).
lung adenocarcinoma (3 papers, 2020 to 2024). A carcinoma that arises from the lung and is characterized by the presence of malignant glandular epithelial cells. "It was found that not only in the lung adenocarcinoma and squamous cell carcinoma but also in most other tumour types, the expression level of RCC1 in cancer was significantly higher than that in surrounding tissues." (PMID 33630417, 2021). "We used siRNA to inhibit the mRNA and protein expression of RCC1 in A549 and H1299 human lung adenocarcinoma cells." (PMID 33630417, 2021). "In vitro, knockdown of RCC1 not only significantly inhibited the proliferation of lung adenocarcinoma cells but also increased the expression levels of p27kip1 and PD‐L1, and decreased the expression level of CDK4 and p‐Rb." (PMID 33630417, 2021). "By bioinformatics analysis, we found that the expression of regulator of chromosome condensation 1 (RCC1) in lung adenocarcinoma was significantly higher than that in normal lung tissue in TCGA and Oncomine databases." (PMID 33630417, 2021). "For example, RCC1 expression is higher in clinical cancers, such as lung adenocarcinoma, than that of normal tissues." (PMID 33102517, 2020). "Therefore, our results suggested that RCC1 should be a hub molecule in the development of lung adenocarcinoma." (PMID 33630417, 2021). "In general, inhibition of RCC1 expression might not only inhibit the development of lung adenocarcinoma but also increase the protein level of PD‐L1, which might sensitize the efficacy of PD‐L1 monoclonal antibody." (PMID 33630417, 2021). "In this study, we found that the high expression of RCC1 in lung adenocarcinoma might increase the proliferation rate of cancer cells, and related to poor prognosis of patients." (PMID 33630417, 2021). "Moreover, we confirmed the much higher expression of RCC1 in lung adenocarcinoma in immunohistochemistry database." (PMID 33630417, 2021). "In addition, based on bioinformatics analysis and literature search, RCC1 is one of the potential biomarkers for identifying primary lung adenocarcinoma." (PMID 33102517, 2020).
pancreatic cancer (3 papers, 2024 to 2025). "First, analysis of TCGA database showed that the RCC1 expression was significantly higher in pancreatic cancer than in normal pancreas tissue." (PMID 41391757, 2025). "Considering our new finding that KRAS down-regulated SIRT3 through the guanine exchange factor RCC1 in vitro, we thus further evaluated the role of RCC1 in affecting pancreatic cancer cell proliferation and tumor growth in vivo." (PMID 41391757, 2025). "Knockdown of RCC1 in pancreatic cancer cells restored SIRT3 expression and impaired tumor formation in vivo." (PMID 41391757, 2025). "These new findings indicate that the down regulation of the RCC1/SIRT3 axis plays a significant role in KRAS-driven pancreatic cancer development." (PMID 41391757, 2025). "Overexpression of KIF11 and RCC1 and underexpression of ADCY1 and SDK1 were detected in ~ 60% of grade 2 pancreatic cancer patients and associated with ~ 60% mortality in stages I and II." (PMID 38741142, 2024). "As such, up-regulation of SIRT3 by abrogating RCC1 might by a potentially effective strategy to overcome resistance to this drug in pancreatic cancer." (PMID 41391757, 2025). "As such, RCC1 could be a potential target for the treatment of pancreatic cancer." (PMID 41391757, 2025). "In particular, the overexpression of KIF11 and RCC1 and the underexpression of ADCY1 and SDK1 were detected in ~ 60% of tumor grade 2 pancreatic cancer patients and associated with around 60% mortality in stages I and II, which shows they can be early-diagnosis markers for pancreatic cancer." (PMID 38741142, 2024). "Importantly, high expression of RCC1 was significantly correlated with poor clinical outcome, as evidenced by lower overall survival in pancreatic cancer patients with high RCC1 expression, suggesting that RCC1 might play a major role in pancreatic cancer development." (PMID 41391757, 2025). "The overexpression of KIF11 and RCC1 and the underexpression of ADCY1 and SDK1 were detected in ~ 60% of tumor grade 2 pancreatic cancer patients." (PMID 38741142, 2024). "Analysis of The Cancer Genome Atlas (TCGA) datasets revealed that high expression of RCC1 or ACTL6A was significantly correlated with poor survival of pancreatic cancer patients (p < 0.05), whereas RUVBL2 expression was not correlated with the patient survival (p = 0.4524)." (PMID 41391757, 2025). "A knockdown of RCC1 in PANC-1 cells could significantly upregulate SIRT3 expression and inhibited cancer cell proliferation in vitro and tumor growth in vivo, indicating a critical role of RCC1 in pancreatic cancer development." (PMID 41391757, 2025).
renal cell carcinoma (3 papers, 2015 to 2021). "The diagnosis of renal cell carcinoma was confirmed by the diffuse and strong staining for renal cell carcinoma markers (Pax-8, RCC-1, and CD10)." (PMID 32908722, 2020).
sarcoma (3 papers, 2021 to 2024). A usually aggressive malignant neoplasm of the soft tissue or bone. "Finally, a prognostic model for sarcoma patients was constructed using six hub genes: risk score = 0.05 × VEGFA + 0.25 × HMGB3 + 0.22 × FASN + 0.40 × RCC1 + 0.46 × NETO2-0.10 × BIRC5." (PMID 38240704, 2024). "In addition, the high expression of RCC1 is also associated with poor disease-free survival (DFS) of sarcoma and better DFS of bladder cancer (all p < 0.05)." (PMID 34298996, 2021). "A total of 140 primary sarcoma samples were stratified into the RCC1-high group and RCC1-low group based on the mean value of RCC1 abundance." (PMID 38561375, 2024). "Together, these results suggest that RCC1 might function as an oncogene in soft-tissue-sarcoma cells by promoting the cell proliferation, migration and invasion." (PMID 38561375, 2024). "As far as we know, the function of HMGB3, FASN and RCC1 in sarcoma has not been reported." (PMID 38240704, 2024).
bladder cancer (2 papers, 2016 to 2021). "In X RCC1 rs25487, compared to the CC genotype, CT genotype was associated with a decreased risk of bladder cancer (P = 0.002, adjusted OR = 0.48, 95% CI: 0.31–0.76)." (PMID 27153553, 2016).
non-small cell lung carcinoma (2 papers, 2021). A group of at least three distinct histological types of lung cancer, including non-small cell squamous cell carcinoma, adenocarcinoma, and large cell carcinoma. "However, a survival analysis showed the opposite result: high expression of RCC1 was associated with a poor prognosis of non-small cell lung cancer." (PMID 34924821, 2021). "A recently conducted study in non-small cell lung cancer pointed out that downregulation of RCC1 can increase the sensitivity of immunotherapy by upregulating PD-L1 through the p27kip1/CDK4 axis." (PMID 34298996, 2021). "A previous study found that downregulation of RCC1 could sensitize immunotherapy by upregulating PD-L1 via the p27kip1/CDK4 pathway in non-small cell lung cancer, and the expression of RCC1 was inversely related to the amount of immune cell infiltration." (PMID 34924821, 2021).
soft tissue sarcoma (2 papers, 2024 to 2025). A malignant neoplasm arising from muscle tissue, adipose tissue, blood vessels, fibrous tissue, or other supportive tissues excluding the bones. "Finally, we validated that suppression of RCC1 could significantly inhibit the growth of soft-tissue sarcoma in vivo, which was largely compromised by introduction of nondegradable form of Skp2." (PMID 38561375, 2024). "Together, these data indicate that RCC1 knockdown suppresses the proliferation, migration and invasion of soft-tissue sarcoma cells through compromising the protein stability of Skp2, and that RCC1 and Skp2 might be functionally related in the oncogenesis of soft-tissue sarcoma." (PMID 38561375, 2024).
testicular germ cell tumor (2 papers, 2019 to 2020). A germ cell tumor arising from the testis. "Moreover, a pathological fusion transcript between regulator of chromosome condensation 1 (RCC1) and HENMT1 was identified in testicular germ cell tumors." (PMID 30764532, 2019).
breast tumors (1 paper, 2021). "In fact, RCC1 blockade is being investigated as a potential therapeutic strategy against aggressive breast tumors." (PMID 34924821, 2021).
cholangiocarcinoma (1 paper, 2021). A carcinoma that arises from the intrahepatic biliary tree (intrahepatic cholangiocarcinoma) or from the junction, or adjacent to the junction, of the right and left hepatic ducts (hilar cholangiocarcinoma). "Of note, cholangiocarcinoma and PCPG cases with genetic alternation show a copy number deletion of RCC1." (PMID 34298996, 2021).
clear cell renal cell carcinoma (1 paper, 2023). "However, the prognostic value and exact function of RCC1 remain unknown in patients with clear cell renal cell carcinoma (cRCC)." (PMID 37747077, 2023).
embryonal carcinoma (1 paper, 2019). A non-seminomatous malignant germ cell tumor characterized by the presence of large germ cells with abundant cytoplasm resembling epithelial cells, geographic necrosis, high mitotic activity, and pseudoglandular and pseudopapillary structures formation. "The role of Rcc1 in ESCs is not characterized before, yet a paper has found it may be a pluripotency marker in embryonal carcinoma cell line." (PMID 31151411, 2019).
gastric tumor (1 paper, 2020). "In gastric tumor tissues, the results of differential methylation hybridization microarray analysis reflected the hypermethylation level of the RCC1 gene at the lesion site, mainly at the ninth CpG site, which caused RCC1 silencing." (PMID 33102517, 2020).
inflammatory skin disease (1 paper, 2021). Inflammatory skin disorders covers a broad category that includes many conditions ranging in severity, from mild itching to grave medical health complications These disorders are common in people of all ages and races. "In AZ(−) conditions, THDC up-regulated genes increased as part of the unhealthy skin signature (P < 0.01), which is a set of genes increased in diverse types of inflammatory skin disease (e.g., SOD2, PRMT1, RCC1)." (PMID 34445461, 2021).
melanoma (1 paper, 2020). A malignant, usually aggressive tumor composed of atypical, neoplastic melanocytes. "The gray scale quantification of these images showed that the expression of FKBP4 and RCC1 was significantly upregulated in melanoma, while the expression of PRADC1 was slightly upregulated, and the expression of GBP1 was downregulated (P < 0.05)." (PMID 33194692, 2020). "Therefore, we believe that the role of RCC1 in melanoma may be related to its important positive regulation function of cell cycle, and its increased expression will promote the disordered proliferation of tumor cells, and even mediate the resistance of tumor cells to treatment." (PMID 33194692, 2020). "These 13 mRNAs were further analyzed by multivariate COX proportional hazard regression analysis, and finally, four hub mRNAs that could be used to predict melanoma prognosis were selected: PRADC1, FKBP4, RCC1, and GBP1." (PMID 33194692, 2020).
meningioma (1 paper, 2020). A generally slow growing tumor attached to the dura mater. "Hence, loss of RCC1 is associated with the development of microcystic meningioma, and this alteration was observed in one of our samples, classified as microcystic, a type which corresponds to 1% of all grade I meningiomas." (PMID 32670372, 2020).
neuroblastoma (1 paper, 2021). Neuroblastoma (NB) is the most common solid, extracranial childhood tumor. "Most small GTPases require guanine nucleotide-exchange factors (GEFs) for activation, and EFGR associated with guanine nucleotide exchange factor 16 (neuroblastoma, ephexin 4) and regulator of chromosome condensation 1 (RCC1)." (PMID 34724825, 2021).
osteosarcoma (1 paper, 2023). A usually aggressive malignant bone-forming mesenchymal neoplasm, predominantly affecting adolescents and young adults. "Eight out of the 54 hub‐genes (ASPM, CENPF, KIF14, KIF20A, RCC1, SMC2, SRC, and TOP2A) were significantly decreased after NACT (criteria: |fold change| ≥ 2 and adjusted p value < 0.05), consistent with the central role of these hub genes in osteosarcoma." (PMID 37457661, 2023).
yolk sac tumour (1 paper, 2025). "In this study, another fusion, RCC1-HENMT1, was also observed in a significant number of TGCT tissues of undifferentiated histological classes of TGCT, including all GCNIS samples, and all other TGCT samples, excluding on yolk sac tumour." (PMID 39809819, 2025).